IL1B (interleukin 1 beta)
Diseases named in the same sentence as IL1B in open-access papers (continued):
Sharing a sentence is not in itself a finding about the gene and the disease.
infection (continued). "After C50041ΔtrmE infection, there was a significant increase in the mRNA of TNF-α (p < 0.01) on day 1 and IL-1β (p < 0.001) on day 7, but the mRNA of IL-1β (p < 0.05) and IFN-γ (p < 0.05) was significantly reduced on day 4 compared to that of SE (C50041)." (PMID 40731965, 2025). "One day after infection, the hemogram is still normal, but circulating TNF-α, IL-1β, and CCL2 were markedly lower in infected hypothyroid mice with respect to euthyroid mice, while CXCL10 levels were higher." (PMID 41263555, 2025). "In a low-dose infection model, AIM2 inhibition reduced IL-1β and IL-18 production, LDH release, and tissue pathology." (PMID 41225161, 2025). "IL-1β and TNF-α are two important proinflammatory cytokines that participate in the regulation of inflammatory response at the early infection period." (PMID 40963585, 2025). "Moreover, IL-1β production can result from activation of inflammasomes other than NLRP3 or via inflammasome-independent pathways, raising concerns that IL-1β-specific blockade may impair host defense and increase infection risk." (PMID 41231359, 2025). "The mRNA level of cytokines, including IL-1β, IL-10, IL-8, TNF-α, IFN-α, and IFN-γ, was detected in MARC-145si14-3-3γ and MARC-145siNC cells following infection with TA-12." (PMID 40704900, 2025). "We previously reported that the infection induced TNF-α, IL-17A, and IL-1β expression, which potentially activates the NF-κB signaling pathway." (PMID 40127923, 2025). "The data indicated that IL-1β, IL-6, IL-8, IL-18, TNF-α, and COX-2 mRNA levels in the spleen in the infection group were significantly upregulated (p < 0.001)." (PMID 40427533, 2025). "Infection of primed murine neutrophils with Y. pseudotuberculosis ΔyopM resulted in activation of the pyrin inflammasome, GSDMD pore formation, IL-1β release and pyroptosis." (PMID 39883598, 2025). "IL-6, IL-1β, and STAT1 expression levels rapidly increased post-infection, peaking at 2 dpi with 11.84-fold, 13.22-fold, and 6.84-fold (all p < 0.05) elevation, respectively." (PMID 41011502, 2025). "One day after infection, the expression of Cxcl1, Cxcl2, Cxcl5, TNF-α, and IL-1β were 15 – 50-fold higher in lungs of Mki67WT mice exposed to hyperoxia when compared to Mki67WT mice exposed to room air." (PMID 40494897, 2025). "This reduction was confirmed at the protein level in HT29 cells, with a significant decrease in IL1β and CASP1 expression observed 2 h post-infection (p < 0.05) and further downregulation at 24 h post-infection (p < 0.01)." (PMID 39943201, 2025). "To evaluate the mechanism through which N. caninum infection regulates IL-1β, we tested MCC950 (an NLRP3 inhibitor), VX765 (a CASP1 inhibitor), and SN-50 (an NF-κB inhibitor) in THP-1 cells following infection with parental strain Nc1 and NcGRA7KO." (PMID 41357231, 2025). "Despite partial IgG induction upon repeated dosing, PEGylated phages maintained superior PK and significantly suppressed infection-driven IL-6, IFN-γ, TNF-α, and IL-1β, normalizing cytokine profiles toward baseline." (PMID 41309396, 2025). "Our results showed that baicalin reduced the expression of the pro-inflammatory cytokines tumor necrosis factor alpha (TNF-α), interleukin-1 beta (IL-1β), and interleukin-6 (IL-6) in PPMCs and the peritoneum of piglets after GPS infection." (PMID 40867785, 2025). "Quantitative PCR analysis revealed increased mRNA levels of proinflammatory cytokines and chemokines (Tnf, Il6, Il1b, Ccl2, Cxcl1, and Cccl2) in SARS-CoV-2-infected lungs compared with those in naïve lungs on days 2 and 5 post-infection." (PMID 40162785, 2025). "The IL-1β, IL-18, and TNF-α protein levels were reduced in the Pro10, Pro20, Pro40, Amo20, Pro20 + Amo20, and Bai100 groups compared with the infection group (p < 0.05) (except TNF-α in the Pro10 group)." (PMID 40305201, 2025).
infection (continued). "Consistently, the LASSO regression retained five of these six parameters as the strongest predictors of infection status: urea (coefficient = 0.41), IL-10 (0.53), TNF (0.49), CCL3 (0.38), and IL-1β (0.33)." (PMID 41279035, 2025). "In the early stage of infection, ELISA results showed that exogenous PGD2 significantly promoted the secretion of TNF-α, IL-1β, and IL-6 in BMDMs and endometrial tissues, suggesting its role in enhancing the inflammatory response during early infection." (PMID 40874199, 2025). "ELISA results indicated that the cytokine levels of IL-1β, IL-6, and TNF-α in the serum of mice remained relatively stable at 6 h post-infection." (PMID 40170927, 2025). "Cells were harvested and analyzed for infection efficiency based on GFP expression by flow cytometry, and the culture supernatants were harvested to measure IL-1β production by ELISA and LDH release." (PMID 40920844, 2025). "The up-regulation amplitude was IL-6 > IL-1β > TNF-α, and the up-regulation amplitude increased with extended infection time within 18 h." (PMID 40663568, 2025). "IFN-β was present at very low levels in mice before infection (pre), while TNF-α, IL-1β, and IL-6 were undetectable." (PMID 40124358, 2025). "A significant downregulation of HIF1A, NLRP3, GBP1 and ASC, and upregulation of IL1B was observed in HIF1A‐KD macrophages, while downregulation of ASC was noted in GBP1‐KD macrophages infected with HN878, compared with CDC1551 infection." (PMID 41287823, 2025). "To determine if TBC1D9’s role during hypervirulent infection extends beyond IL-6, we infected epithelial cells with GAS SSI-1 (M3) and measured the expression of IFN-β, TNF-α, IL-1β, and IL-8." (PMID 41306588, 2025). "This pattern resembles the cytokine-mediated induction reported during Mab infection of THP-1 macrophages, which led to elevated expression of TNF-α, CCL4, IL-8, and IL-1β." (PMID 40762982, 2025). "The levels of proinflammatory cytokines including TNF, IL-1β, IL-6, and MIP-2 were measured in the cell-free supernatants of the P. aeruginosa-infected BMDMs at 3 h post-infection." (PMID 40143103, 2025). "Cytokines such as IL-1β and TNF-α are crucial for recruiting neutrophils and macrophages to the site of infection, promoting phagocytosis and fungal clearance." (PMID 41295183, 2025). "In both the B.1.351 model and the AAV-hACE2-WA1 model, intranasal SARS-CoV-2 infection resulted in increases in pro-inflammatory cytokines (e.g., IL-1β, IFNβ, CXCL10, IFNγ, IL-6, and CCL11) in the hippocampus and cerebrospinal fluid at 7 days post-infection." (PMID 39861887, 2025). "The qPCR experiment showed that the transcription levels of IL-1β, IL-6, and TNF-α in the circ-ZNF277 suppressed THP-1 cells were lower than those in the control THP-1 cells at 0, 12, and 24 h post-infection (p < 0.001)." (PMID 39996735, 2025). "In the mock infection group, however, the Winter PM exposure induced elevated IFN-γ, IL1-β, IL-8, IL-4, IL-5, IL-10, and VEGF-A at the 24 h timepoint." (PMID 40671793, 2025). "At the serum inflammatory level, ST infection (ST group) upregulated IFN-γ, IL-1β, and IL-8 expression compared to in the CTL group." (PMID 40563970, 2025). "Real-time PCR analysis of mRNA from whole brain tissue revealed elevated expression of proinflammatory mediators ll-6, Il-1β, Ccl2, Cxcl9, and Cxcl10 in both the WT and eNOS+/− mice 3 days post-MA10 infection." (PMID 40573374, 2025). "The IL-1β, IL-18, and TNF-α mRNA levels were decreased in the Pro10, Pro20, Pro40, Amo20, Pro20 + Amo20, and Bai100 groups compared with the infection group (p < 0.001)." (PMID 40305201, 2025). "Following VMV infection, BAL macrophage numbers are elevated and AlvMφ display an activated phenotype with secretion of IL-8, IL-6, IL-10, GM-CSF, TNF-α, IL-1β, and TGF-β." (PMID 39796262, 2025). "post-infection, hv-WAD significantly increased the production of TNF-α and IL-1β (p < 0.01) in response to both strains." (PMID 41373747, 2025).
infection (continued). "Pro-inflammatory factors, such as IL-1β, IL-6, and TNF-α, can mediate host’s inflammatory response by rapidly generating an immune response after pathogen infection." (PMID 40821810, 2025). "Serum protein levels of IL-1β (L), TNF-α (M), and IL-6 (N) were examined through ELISA assays 24 hr post infection." (PMID 39998486, 2025). "For example, OmTRIM25 and finTRIM2 were significantly up-regulated after two days of infection, while IL-1β and TNF-α2 reached their peaks of expression at four and six days post-infection, respectively." (PMID 41514764, 2025). "In fact, inhibition of ADA by EHNA after 3 h of infection with TcdA in the ileum of mice reduces tissue damage, neutrophil infiltration, and the level of the pro-inflammatory cytokines TNF-α, IL-1β, as well as the expression of NOS2, NF-κB and PTX3." (PMID 40646589, 2025). "While IL-1β, IL-6, and TNF-α levels were similar at admission, IL-1β and TNF-α significantly increased during follow-up, indicating immune activation in later infection stages." (PMID 40611327, 2025). "The ELISA results revealed that EPEC66 infection significantly increased the levels of the pro-inflammatory cytokines TNF-α, IL-1β, and IL-6 in the ileum, compared with those in the NC group (p < 0.01)." (PMID 41373958, 2025). "The expression of TNF-α, IL-1β, IL-6, IL-10, TGF-β, and hepcidin mRNA in WT increased sharply and reached a peak on day 1 post-infection with A. hydrophila, followed by a decrease." (PMID 40298788, 2025). "Infection with IAV leads to a distinct immune response in the lungs, production of pro-inflammatory cytokines and chemokines (IL-1b, IL-6, G-CSF, KC, MIP-1b), and decreased bronchodilation." (PMID 41567998, 2025). "To determine the influence of coexistent Ss infection on type 1, type 17, and proinflammatory cytokines in TBI, we measured the QFT supernatants levels of IFN-γ, TNF-α, IL-2, IL-17, IL-22, IL-1α and IL-1β in TBI+Hel+ and TBI+Hel- individuals." (PMID 41583474, 2025). "The secretion of IL-1β, IL-6, and TNF-α was detected using ELISA, while the intracellular survival of Mtb was assessed by CFU counting 24 h post-infection." (PMID 39996735, 2025). "Microglia can resist pathogen infection through releasing proinflammatory cytokines such as IFN-γ and interleukin-1 beta (IL-1β), and recruiting immune cells from the peripheral circulation." (PMID 40760662, 2025). "Analysis of inflammatory mediators in NHBE culture supernatants (Luminex multiplex assay) revealed that IL1β, IL1α, and CXCL1 were significantly elevated in NHBEA/A cultures compared to NHBEG/G cultures following infection with Cal/09 and HK/68." (PMID 40627391, 2025). "After infection of mice with the HY/HA-ΔL226/R229I strain, levels of TNF-α decreased at 3 dpi, while IL-6 and IL-1β levels increased at 5 dpi." (PMID 40338080, 2025). "Before the infection, TNF-α and IL-1β expression significantly increased in groups fed oregano-supplemented diets compared to the control, whereas NF-κB expression levels remained unaffected." (PMID 41188425, 2025). "Another study demonstrated that Mtb-induced IL-1β production in BMDMs was dependent on ESAT-6, and that the effects of ESAT-6 on IL-1β was possibly regulated by an infection-inducible inflammasome complex containing NLRP3, ASC, and caspase-1." (PMID 41011275, 2025). "Pro-inflammatory cytokines and chemokines like IL-1β, IL-8, GRO-α, RANTES, MIP-1α, MCP-1, and IFN-γ have been detected in cell culture supernatants and plasma and mucosal surfaces after infection in humans (39, –, 42)." (PMID 41060027, 2025). "The infection triggers a systemic inflammatory response, including elevated IL-6, TNF-α, and IL-1β, which amplifies vascular injury." (PMID 41012624, 2025). "On day 3 of infection by R. oryzae, the CFU in liver and spleen exhibited weak positive correlations in all cytokines evaluated, with IL-1β (0.43) in spleen being the most prominent." (PMID 41156648, 2025).
infection (continued). "In this study, after the administration of AB-WE to goldfish and following pathogen infection, the expression of inflammation-related factors (IL-6, IL-8, TNF-α, and IL-1β) displayed a significant reduction (p < 0.05) in visceral tissues." (PMID 40805047, 2025). "Their production in the liver is stimulated through IL-1β, IL-6, and TNF-α, in response to infection, inflammation, or injury." (PMID 40943382, 2025). "Our findings indicated that MPXV infection promoted CASP1-dependent cleavage of CASP1 and the release of the inflammasome-driven cytokines IL-1β and IL-18, suggesting that MPXV is involved in inflammasome activation." (PMID 41225161, 2025). "When the piglets were administered levamisole or baicalin, the mRNA expression levels of IL-1β, IL-18, and TNF-α in the blood vessels were weakened compared to the infection group (p < 0.001)." (PMID 40427615, 2025). "We found higher IL-1b levels in adult serum and PBMC cultures post-infection, correlating with age and promoting IL-6, IL-9, and IL-17A secretion when combined with IFNa." (PMID 40834853, 2025). "Whereas IL-1β release from NLRP11−/− macrophages was significantly reduced at 1, 2, 4, and 6 h of infection, cell death was significantly lower only at 6 h of infection." (PMID 40272180, 2025). "The results demonstrated that infection of RAW 264.7 cells with M. smegmatis led to increased production of the pro-inflammatory cytokines TNF-α and IL-1β." (PMID 40005637, 2025). "In lung tissue, IL1B, IL6, IL10, CXCL2, CCL3 and CCL5 levels also rose in both genotypes following infection, although these markers were significantly lower in TLR7 KO mice." (PMID 40442368, 2025). "Here, we found that 10 mM of L-serine significantly reduced the expression of inflammatory cytokines (mainly IL-1β and TNF-α) in P. multocida—infected macrophages (the most significant changes were at 12 h post infection)." (PMID 40267013, 2025). "IL-1β, IL-18, and LDH levels in the BALF 5 days after MPXV infection exhibited an AIM2-dependent effect." (PMID 41225161, 2025). "Following the infection of RAW264.7 cells with SFTSV at the MOI of 200 for 24 or 48 h, the levels of IL-1β, IL-6, IL-10, TNF-α, and MCP-1 were measured by using qPCR." (PMID 41472750, 2025). "To better understand the differences observed between Il-1β–/– and Il-1r–/– mice, we extended our analysis to multiple time points after SARS-CoV-2 P21 infection." (PMID 40016339, 2025). "We also measured inflammatory cytokine levels (TNF-α, IFN-γ, IL-1β, IL-6, IL-10, and IL-12) in the BALF supernatant 3 days post-infection." (PMID 39655914, 2025). "In parallel, proinflammatory cytokines (IL-1β, TNF-α, IL-6, IFN-α, and IFN-β) were measured, only IL-6 was significantly increased following SUCNR1 knockdown upon infection." (PMID 41492386, 2025). "In gECs, E. gingivalis infection increased mucin (MUC1: 3.6×, MUC21: 14.4×) and interleukin secretion (IL-8, IL-1B: >6×, P = 0.019)." (PMID 40116481, 2025). "Upon infection with wild-type (WT) Salmonella, WT THP-1 cells pretreated with either YVAD or ZVAD had significantly reduced levels of IL-1β release and cell death compared to infected WT cells pretreated with the vehicle control." (PMID 40162563, 2025). "Levamisole significantly inhibited IL-1β, IL-6, IL-8, IL-18, TNF-α, and COX-2 mRNA expressions in the spleen compared to the infection group (p < 0.001)." (PMID 40427533, 2025). "Upon infection of PBMCs, HIV-1ADA induced significantly higher levels of pro-inflammatory cytokines IL-1α, IL-1β, IL-6 and TNF-α as measured via Luminex assay." (PMID 40313367, 2025). "On the other hand, pro-inflammatory cytokines IL-1β, IL-7, IL-18, and chemokines MCP-1 and MIP-1α were upregulated after infection with rCDC-9 P11 compared to rCDC-9 P45." (PMID 41060027, 2025).
infection (continued). "Several cytokines (TNF, IL-1β) and chemokines (CXCL10, CCL2, CCL5) were reduced in the brains of Rag1–/– animals at day 14 after infection, which were restored or exceeded WT levels mainly with Th1 adoptive transfer, whereas Th17 cells were less effective." (PMID 39989461, 2025). "Infection of both macrophages and microglia with either replication-competent or single-cycle HIV-1 induced IL-1β secretion, which was attenuated when cytoplasmic expression of viral icRNA was prevented." (PMID 40920844, 2025). "Serum protein levels of IL-1β (B), TNF-α (C), and IL-6 (D) were examined through ELISA assays 24 hr post infection." (PMID 39998486, 2025). "There was robust upregulation of proinflammatory cytokine genes (TNF–α, IL–1β, and IL–6) and chemokine genes (RANTES, MIP–1α, and MIP–1β), reflecting a strong inflammatory response that recruits immune cells to the site of infection." (PMID 41214723, 2025). "During the later stages of infection, TRIM38 negatively regulates the TLR3/4 signaling, consequently suppressing the production of proinflammatory cytokines including TNF-α, IL-1β, and IL-6." (PMID 40006954, 2025). "The expression of IL-1β and IL-6 in Vero and DF-1 cells is upregulated during early ARV infection, promoting cell migration and infection spread through chemotactic response regulation." (PMID 40059215, 2025). "We confirmed expression levels of a selected gene by qPCR analysis of IL-1β and the type 1 interferon (IFN-β) response during the early time points of infection." (PMID 40080408, 2025). "The results demonstrated low Il1b, Ifng, and Cd86 mRNA expression during ME49 ∆bfd2 strain infection." (PMID 40906736, 2025). "However, their overall efficacy lags behind JAK inhibitors (notably in ACR20/70 responses), and safety concerns—including higher rates of severe adverse events and treatment discontinuation—may relate to suppression of IL-1β’s broad physiological roles (e.g., infection defense)." (PMID 40520203, 2025). "In an inflammatory context, resident cells, such as macrophages, release a cascade of pro-inflammatory cytokines, including IL-1β and TNF-α, which act as signaling molecules, coordinating the host’s response to injury or infection." (PMID 39409022, 2024). "Pro-inflammatory interleukins, such as IL-1β, IL-6, and TNF-α, are key players in initiating and amplifying immune responses during infection or tissue injury." (PMID 38251210, 2024). "In rat neuronal cells cultured in vitro, it has been observed that, in response to EV infection, both microglia and astrocytes can induce an inflammatory response through the secretion of NO, TNF-α, and IL-1β." (PMID 38248274, 2024). "At 4 h post-infection, all stimuli induced significantly higher gene expression levels of IL-8, TNF-α, MCP-1, and IL-1β." (PMID 39035711, 2024). "Such exacerbation of the inflammatory response during infection with DENV and SARS-CoV-2 can explain the increased levels of secreted IL-1β observed in our study." (PMID 39583156, 2024). "During infection, ATF3 actively adjusts innate immunity by enhancing the expression of TNF-α, IL-1β, and IFN-γ, thereby facilitating bacterial clearance." (PMID 38255898, 2024). "After infection with ASFV, the concentrations of porcine TNF-α and IL-1β were significantly elevated in supernatants of PAMs and BMDMs in a time-dependent manner." (PMID 38952452, 2024). "In this context, infection with the T. gondii clonal types I and II showed that the activation of P2X7 receptor produced the inflammatory mediators as interleukin (IL)-1β, IL-12, IFN- γ, the reactive oxygen species (ROS), and lead to parasite control." (PMID 39267751, 2024). "Analysis of cytokines indicated a global PCLS age-effect and PAO1 infection-effect for CXCL1, IL-6, and IL-1β, while for TNF-α only a global infection-effect was observed." (PMID 38178102, 2024).